FYN (FYN proto-oncogene, Src family tyrosine kinase)
Diseases named in the same sentence as FYN in open-access papers (continued):
Sharing a sentence is not in itself a finding about the gene and the disease.
pancreatic cancer (20 papers, 2018 to 2025). "It has been demonstrated that upregulation of FYN expression is associated with metastasis in human pancreatic cancer." (PMID 36740671, 2023). "The interplay between AKT and FYN pathways is emerging as a key factor in invasive phenotypes in breast and pancreatic cancers." (PMID 39934141, 2025). "In the orthotopic model, IHC analyses showed that FYN expression was significantly higher in KMT2B‐overexpressing pancreatic tumours compared to control tumours (p < .05)." (PMID 40741875, 2025). "Our findings reveal a novel KMT2B/FYN/PI3K/Akt axis through which KMT2B promotes the malignant behaviour of pancreatic cancer." (PMID 40741875, 2025). "In pancreatic cancer cell lines, FYN mediates the AKT pathway via phosphorylation of the ionotropic glutamate receptor subunit 2B (GluN2B) at Ser1303, which subsequently phosphorylates AKT, enhancing tumor survival and progression." (PMID 39934141, 2025). "In silico molecular docking studies support experimental data by elucidating inhibition of an antimicrobial protein (MurB involved in cell wall biosynthesis in S. aureus) and a cancer‐related protein (FYN) specifically increased in pancreatic cancer." (PMID 39479685, 2024). "In pancreatic cancer, FYN coordinates with HnRNPA2B1 and Sam68 to regulate apoptosis and promote proliferation and metastasis of pancreatic cancer." (PMID 36740671, 2023). "FYN stimulates pancreatic cancer progression through phosphorylation of GluN2b and the regulated AKT protein kinase signaling pathway." (PMID 36740671, 2023). "It has been demonstrated that Inhibition of FYN activity and/or hnRNP E1 overexpression decreased metastasis in pancreatic cancer cells, and FYN / hnRNP E1 signaling regulated pancreatic cancer metastasis by affecting variable splicing of integrin β1." (PMID 36740671, 2023). "Inhibition of FYN activation by kinase-inactivating FYN transfection in BxPC3 pancreatic cancer cells reduced liver metastasis in nude mice." (PMID 36740671, 2023). "FYN affects proliferation, apoptosis, migration, and invasion of pancreatic cancer cells through phosphorylation of GluN2b and regulation of the AKT signaling pathway." (PMID 36740671, 2023). "FYN expression levels and downstream protein activation are decreased in pancreatic cancer cells where transcription factor PRDM14 is knocked down." (PMID 36740671, 2023). "It was reported that FYN promoted tumor progression in glioma, melanoma, colon cancer, gastric cancer, and pancreatic cancer through various mechanisms." (PMID 38022584, 2023). "CASP4, FYN, TOB1, and CLEC2B exhibited close associations with infiltrating Treg cells in pancreatic cancer, suggesting their involvement in Treg cell functions." (PMID 37753069, 2023). "Inhibition of FYN expression in pancreatic cancer significantly inhibited proliferation, migration, and invasion of pancreatic cancer cells." (PMID 36740671, 2023). "A study of pancreatic cancer also demonstrated that FYN inhibition promotes the phosphorylation and nuclear localization of hnRNP E1, which ultimately suppresses pancreatic cancer cell metastasis and invasion." (PMID 36498797, 2022). "In particular, lower expression levels of FYN correlated with poor OS in patients with melanoma, head and neck, liver, lung, and pancreas cancers." (PMID 32933107, 2020). "FYN knockdown or inhibition significantly reduces proliferation, migration, metastasis, and invasion in pancreatic cancer models." (PMID 33233470, 2020). "Mechanistic studies exploring the signaling axis of FYN in pancreatic cancer suggest significant modulation of cell cycle and apoptotic behaviors." (PMID 33233470, 2020). "FYN control of BCLx splice factors has further been studied in the pancreatic cancer BxPc3 cell line, where it was shown that inhibition of FYN not only reduces SAM68 phosphorylation, it also decreases hnRNP A2B1 expression." (PMID 29361709, 2018).
pancreatic cancer (continued). "Furthermore, another ambitious inhibitor candidate for the FYN protein against pancreatic cancer cell lines was identified as keracyanin chloride with its high binding affinity, low binding free energy, and highest H bond‐forming ability." (PMID 39479685, 2024). "FYN inhibition reduces the growth of pancreatic cancer cells." (PMID 37324495, 2023). "Inhibition of FYN activity inhibits pancreatic cancer cell proliferation." (PMID 36740671, 2023). "Inhibition of FYN activity in pancreatic cancer is upregulated by P21-activated kinase 1 expression and promotes phosphorylation and nuclear localization of hnRNP E1, leading to the construction of a spliceosome complex that affects variable splicing of integrin β1." (PMID 36740671, 2023). "Upregulation of FYN expression in pancreatic cancer is associated with pancreatic cancer metastasis, and in pancreatic cancer cells, reduced or absent FYN activity significantly inhibited liver metastasis in nude mice." (PMID 36740671, 2023). "Inhibition of FYN activity inhibits metastasis in pancreatic cancer." (PMID 36740671, 2023). "Evidence suggests that the role of FYN in pancreatic cancer is consistent with the role of FYN in other cancers, although its mechanism in pancreatic cancer may be somewhat unique." (PMID 33233470, 2020). "FYN expression is upregulated in many pancreatic cancers and its kinase activity is enhanced." (PMID 33233470, 2020). "The further novel funding of the TIMER database was that the expression level of FYN, MAPK, and PIK3CA correlate with immune infiltrates of B cell, CD8+ cell, macrophage, neutrophil, and dendritic cell in pancreatic cancer patients." (PMID 36091768, 2022). "According to the previous study, FYN, LRSAM1, and SEMA6C serve as poor prognostic biomarkers in pancreatic cancer, whereas ERAP2, MET, IL20RB, and CXCL11 indicate improvements." (PMID 36428747, 2022). "Among these genes, we noticed that FYN, a proto-oncogene and a Src family tyrosine kinase, was reported to involved in EMT and to promoted cancer metastasis in colon cancer, gastric cancer, and pancreatic cancer." (PMID 35526051, 2022).
prostate carcinoma (15 papers, 2014 to 2025). A carcinoma that arises from epithelial cells of the prostate gland. "FYN is a member of the Src family kinases, which have been implicated in various cancer types, including breast, lung, colon, and prostate cancer, among others." (PMID 37324495, 2023). "In silico analysis of FYN expression in prostate cancer cell line databases revealed an association with the expression of neuroendocrine (NE) markers such as CHGA, CD44, CD56, and SYP." (PMID 26624980, 2015). "ABI1 can also inhibit EMT in prostate cancer by suppressing FYN-signal transducer and activator of transcription 3 (STAT3) activation by non-canonical WNT signaling through a high affinity interaction between the FYN SH2 domain and ABI1 pY421." (PMID 39354505, 2024). "FYN is downstream of the HGF/MET signaling loop, and HGF can effectively regulate FYN activity, which promotes prostate cancer biology by promoting cell growth and regulating targeted chemotaxis-translocation components in prostate cancer biology." (PMID 36740671, 2023). "FYN modulates imatinib resistance in prostate cancer patients through interaction with miR-128/193a-5p/494." (PMID 36740671, 2023). "FYN promotes the maintenance of the neuroendocrine phenotype of tumor cells in progressive prostate cancer as well as Vascular metastasis of cancer." (PMID 36740671, 2023). "Computational analysis of FYN expression in the prostate cancer cell line database demonstrated a correlation between neuroendocrine (NE) markers such as CHGA, CD44, CD56, and SYP expression." (PMID 36740671, 2023). "miR-466 overexpression significantly reduces the expression of a network of transcription factor RUNX2 target genes, including FYN, and inhibits tumor growth and bone metastasis in prostate cancer." (PMID 36740671, 2023). "FYN and its downstream molecular signaling pathway proteins are upregulated in prostate cancer expression." (PMID 36740671, 2023). "FYN expression levels of both mRNA and protein were significantly higher in prostate cancer cells than in normal cells." (PMID 36740671, 2023). "In prostate cancer, FYN overexpression, in turn, promotes thyroid cancer cells in colon cancer, and FYN induces early adhesion in colon cancer cells." (PMID 36740671, 2023). "FYN over-expression was demonstrated in prostate cancer and suggested as an interesting therapeutic target." (PMID 32933107, 2020). "Early in 2010, Yoshihito and colleagues revealed that FYN is highly expressed in prostate cancer and possibly leads to a more advanced tumor stage." (PMID 31285693, 2019). "FYN is a SRC family kinase (SFK) that has been shown to be up-regulated in human prostate cancer (PCa) tissues and cell lines." (PMID 26624980, 2015). "Our group has already demonstrated the capacity for FYN to drive metastasis and growth in prostate cancer." (PMID 26624980, 2015). "Further, our data suggest a unique mechanism of COX2 regulation by FYN in prostate cancer, since FYN expression in comparison to other Src family kinases has been shown to be upregulated in the progression to cancer from both normal epithelium and PIN." (PMID 24970799, 2014). "The major finding of this paper is that COX2 activity can be regulated also at the post-translational level in prostate cancer, through direct phosphorylation by the oncogenic kinase of the Src family FYN." (PMID 24970799, 2014). "In summary, our studies suggest that FYN/COX2 interaction is a novel molecular target in prostate cancer." (PMID 24970799, 2014). "This is consistent with other studies showing that FYN can partner with other signaling molecules such as FAK and paxilin, which are upregulated in prostate cancer overexpressing FYN." (PMID 24970799, 2014). "FYN contributes to vascular metastasis in progressive prostate cancer." (PMID 36740671, 2023). "However, current studies mainly favor FYN as a proto-oncogene in prostate cancer with oncogenic activity." (PMID 36740671, 2023).
prostate carcinoma (continued). "Interestingly, FYN has been shown to be an important effector in the HGF/MET signaling axis that acts as a crucial oncoprotein in prostate cancer metastasis." (PMID 32811808, 2020). "We further suggest that regulation of COX2 activity by FYN could contribute to the progression of prostate cancer." (PMID 24970799, 2014). "Additionally, studies have reported that overexpression of FYN results in promotion of the anti-apoptotic activity of Akt, and Akt activation is detected in prostate cancer." (PMID 24970799, 2014). "However, it has been demonstrated that the FYN tyrosine kinase gene at chromosome 6q21 is a novel candidate tumor suppressor in prostate cancer and that FYN is downregulated by chromosomal deletion and promoter hypermethylation and expression in prostate cancer." (PMID 36740671, 2023). "However, FYN is downregulated and acts as a tumor suppressor in prostate cancer." (PMID 37016377, 2023). "However the mechanisms of how aberrant FYN function leads to dysregulated Akt activation in prostate cancer are unknown." (PMID 24970799, 2014). "miR-125a-3p overexpression inhibits the activity of FYN, FAK, and paxillin, thus suppressing prostate cancer metastasis." (PMID 36740671, 2023). "The FYN protein plays a role in promoting cancer by regulating the translation and activity of COX2 in prostate cancer." (PMID 33456463, 2020). "Then, we evaluated the gene expression profiles for the six HUB nodes (ABL1, EP300, FYN, MYC, PSMB2, and SRPK2) in all the prostate cancer cells, compared to normal prostate EPN cells." (PMID 32933107, 2020). "Clinical samples from prostate cancer patients demonstrated that FYN, FAK and PXN expression levels were both increased with significant correlations, hence, FYN might be a prostate cancer molecular target." (PMID 36740671, 2023). "By activating FYN, HGF/MET promotes the progression of prostate cancer." (PMID 36740671, 2023). "In prostate cancer, FYN and other SFKs have been shown to mediate extracellular interactions driven by various molecules including IL-8, c-Met, EGFR and integrins, contributing to metastatic transformation of prostate cancer." (PMID 24970799, 2014). "Studies of FYN in prostate cancer have not been entirely consistent, with some studies suggesting that FYN is proliferative and metastatic in prostate cancer, while others suggest that FYN expression is downregulated in prostate cancer and is a tumor suppressor in prostate cancer." (PMID 36740671, 2023).
Alzheimer disease (10 papers, 2014 to 2025). A progressive, neurodegenerative disease characterized by loss of function and death of nerve cells in several areas of the brain leading to loss of cognitive function such as memory and language. "FYN is strongly implicated in Alzheimer’s disease and other neurodegenerative tauopathies." (PMID 32929078, 2020). "FYN is also strongly implicated in neurodegenerative diseases such as Alzheimer’s disease." (PMID 32929078, 2020). "Many previous studies have demonstrated the relationship betweenpolymorphism in the FYN gene and phosphorylation of Tau protein, oneimportant etiology for Alzheimer’s disease." (PMID 40110380, 2025). "Src family tyrosine kinases regulate many signaling pathways and FYN itself has been shown to be important in cancer and Alzheimer's disease." (PMID 36346145, 2022). "In addition to being used in numerous oncology clinical trials, saracatinib has been explored as a FYN kinase inhibitor in a phase II study of patients with mild-to-moderate Alzheimer’s disease at doses up to 125 mg daily for 12 months (NCT02167256)." (PMID 33705358, 2021).
glioma (10 papers, 2019 to 2024). A benign or malignant brain and spinal cord tumor that arises from glial cells (astrocytes, oligodendrocytes, ependymal cells). "FYN in High expression of FYN in glioma cells reduces immune activation against glioma, and inhibition of FYN improves the efficacy of anti-glioma immunotherapy." (PMID 36740671, 2023). "Recently, FYN knockdown was shown to significantly decrease glioma infiltration by myeloid-derived suppressive cells and to significantly increase survival, in an immune-dependent fashion." (PMID 34763709, 2021). "In our study, we confirmed the pro-cancer role of the FYN/YANK2 axis in glioma progression, and inhibition of YANK2 could significantly delay the progression of glioma." (PMID 38714727, 2024). "Both IDH-A and ATRX-KO glioma show significantly increased expression of FYN." (PMID 34763709, 2021). "Indeed, FYN was previously reported to activate AKT to promote glioma cell proliferation." (PMID 36658114, 2023). "There are nine members in the family, four of which (Src, FYN, YES, and LYN) are expressed in human gliomas." (PMID 31114755, 2019). "Tyrosine-specific phosphoproteomic analysis of IL-33+ tumors showed an increase in a number of phospho-peptides derived from STAT3, CDK1, CDK2, FYN, MAPK14, and MAPK3, some that based on amino acid sequence could be attributed to either human glioma or mouse host origin." (PMID 33020472, 2020).
lung carcinoma (9 papers, 2013 to 2025). "The high expression of AQP1 and FYN in lung cancer tissues increased the possibility of them as true targets of miR-146a-5p." (PMID 31285693, 2019). "In this study, we discovered higher expression levels of FYN in lung cancer than in normal tissues by conducting RT-qPCR for clinical tissues." (PMID 31285693, 2019). "Part of the role of FYN in pro-survival signalling occurs through up-regulation of BCL-XL, an anti-apoptotic protein that we implicated in lung cancer drug resistance." (PMID 29937990, 2018). "This was clinically relevant as LYN and FYN are also overexpressed in lung cancer clinical specimens." (PMID 29937990, 2018). "As SRC expression in lung cancer has previously been examined we focused on the expression of FYN and LYN using two different tissue micro arrays comprising 146 (TMA1) and 138 (TMA2) surgically resected NSCLC cases." (PMID 29937990, 2018). "Analysis of previously published RNA sequencing data from a series of osimertinib tolerant EGFR mutated lung cancer cell lines revealed higher expression levels of FYN and KDM4A in the drug persisters, but not SRC." (PMID 40243589, 2025). "AQP1 and FYN were validated by RT-qPCR to be potential targets of miR-146a-5p in lung cancer." (PMID 31285693, 2019). "In particular, SRC was overexpressed in most lung cancer samples in addition to either LYN or FYN." (PMID 29937990, 2018). "Hence, the expression of AQP1 and FYN tend to be inversely modulated by miR-146a-5p in lung cancer." (PMID 31285693, 2019). "Research has shown that the FYN gene is significantly expressed in tumor samples but has low expression in normal tissues, making PYN a potential new target for anti-lung cancer studies." (PMID 40699827, 2025). "The antitumor functions of FYN, SYK, and PTPN6 in lung cancer have been validated by previous research, which was consistent with our study." (PMID 37279937, 2023). "Currently, we found that two likely miR-146a-5p targets, AQP1 and FYN, showed higher levels in tissues obtained from lung cancer, compared to noncancerous lung tissues." (PMID 31285693, 2019). "In a study of lung cancer cell lines using quantitative phosphoproteomics, approximately 40 different kinases were identified as dasatinib targets, including the SFKs LYN, SRC, YES, FYN, and LCK." (PMID 27756880, 2016).
hepatocellular carcinoma (8 papers, 2014 to 2023). A malignant tumor that arises from hepatocytes. "In hepatocellular carcinoma, FYN-mediated activation of the STAT3 pathway plays an important role in Fzd2-driven EMT and the migration of liver cancer cells." (PMID 36498797, 2022). "We next analyzed the prognostic implication of the HIF regulated genes involved in glutamate signaling in hepatocellular carcinoma (SLC1A1, SLC1A3, GRIA2, GRIA3 and FYN) using PROGgene to analyze the GSE 10141 mRNA expression data set from 80 surgically resected hepatomas." (PMID 25326682, 2014). "It has been shown in another study that increased FYN expression may contribute to hepatocellular carcinoma metastasis.The Wnt5-Fzd2-FYN-Stat3 axis contributes to the EMT program, cell migration, and multiple tumor metastases, and the FYN inhibitor Dasatinib inhibits this process." (PMID 36740671, 2023). "FYN is a proto-oncogene, but its role in tumors, especially hepatocellular carcinoma cells, has not been clarified, and its proposed roles are even contradictory." (PMID 35397600, 2022).
melanoma (8 papers, 2012 to 2025). A malignant, usually aggressive tumor composed of atypical, neoplastic melanocytes. "FYN expression is elevated in melanoma cells, and knockdown of FYN significantly inhibits the proliferation and migration of melanoma cells by downregulating CD147 phosphorylation." (PMID 36740671, 2023). "From the SRC kinases only FYN was higher expressed in the tumors compared to the benign precursor lesion, consistent with its more prominent role in xmrk-driven melanoma." (PMID 22693581, 2012). "YUSIV melanoma cell line, the most sensitive to inhibition by SAB298, required LYN for optimal cell proliferation, whereas there was only at most 50% reduction in growth in response to downregulation of YES and FYN." (PMID 31040916, 2019).